GPX3 (glutathione peroxidase 3)
Diseases named in the same sentence as GPX3 in open-access papers (continued):
Sharing a sentence is not in itself a finding about the gene and the disease.
perinatal asphyxia (1 paper, 2020). A disorder caused by a lack of blood flow or gas exchange to or from the fetus in the period immediately before, during, or after the birth process. "In addition, DIM inhibited apoptosis and oxidative stress accompanying perinatal asphyxia through: downregulation of FAS, CASP-3, CAPN1, GPx3 and SOD-1, attenuation of caspase-9 activity, and upregulation of anti-apoptotic Bcl2 mRNA." (PMID 32816128, 2020).
sarcoidosis (1 paper, 2016). Sarcoidosis is a multisystemic disorder of unknown cause characterized by the formation of immune granulomas in involved organs. "Equally, our own data show higher levels of GPX3 in ILD typically associated with an inflammatory component (HP, sarcoidosis) than in ILD which are considered less associated with inflammation as IPF and SRIF." (PMID 27435875, 2016). "ELISA-based analysis of GPX3 levels in BALF from ILD patients showed consistently low GPX3 levels in patients with IPF and SRIF, but high levels for some HP and sarcoidosis patients." (PMID 27435875, 2016).
schizophrenia (1 paper, 2023). A major psychotic disorder characterized by abnormalities in the perception or expression of reality. "It should also be admitted that among proteins significantly differed in quantitative measure, GPX3, IGKC, C2, and ATRN (adjusted p < 0.01) did not pass the significance level in the validation cohort of subjects with schizophrenia due to large deviation." (PMID 36747015, 2023).
seminoma (1 paper, 2022). A radiosensitive malignant germ cell tumor found in the testis (especially undescended), and extragonadal sites (anterior mediastinum and pineal gland). "NRF2 (rs6721961), GSTM3 (rs1332018), SOD2 (rs4880) and GPX3 (rs8177412) polymorphisms were assessed in 88 patients with testicular GCT (52 with seminoma) and 88 age-matched controls." (PMID 35205816, 2022). "The results of this study also demonstrated that the variant GPX3*TC+CC was a significant risk factor for testicular GCT development and, in particular, seminoma development." (PMID 35205816, 2022). "In this study, the GPX3*TC+CC genotype was significantly associated with the risk of developing testicular GCT, including the risk of developing seminoma." (PMID 35205816, 2022).
serous ovarian cancer (1 paper, 2011). "Using a candidate-based approach, and samples from 3 independent sources, we have identified that the serum protein GPX3, a selenocysteine-containing antioxidant enzyme, is decreased in women with serous ovarian cancer in a stage-dependent manner." (PMID 22017790, 2011). "Our results demonstrate that serum GPX3 is downregulated in serous ovarian cancer." (PMID 22017790, 2011).
squamous cell carcinoma (1 paper, 2020). A carcinoma arising from squamous epithelial cells. "Moreover, COL14A1 methylation (COL14A1me) and GPX3 methylation (GPX3me) levels discriminated adenocarcinomas and squamous cell carcinomas, respectively, from normal samples (p = 0.002 and p = 0.009, respectively)." (PMID 33292587, 2020).
steatosis (1 paper, 2021). Increased lipid within the cytoplasm of cells. "Two selenoprotein genes (GPX2 and GPX3) encompassed in the “glutathione metabolism” pathway had higher expression, and one gene had lower expression (OPLAH) in steatosis, suggesting an increase in glutathione utilisation." (PMID 34869521, 2021).
systemic sclerosis (1 paper, 2021). A chronic disorder, possibly autoimmune, marked by excessive production of collagen which results in hardening and thickening of body tissues. "Patients with systemic sclerosis-related PH displayed lower serum levels of glutathione peroxidase 3 encoded by Gpx3, which was consistent with our observation of a reduction of Gpx3 in lung tissues of PH patients transcriptionally." (PMID 34803695, 2021).
Thromboembolism (1 paper, 2024). The formation of a blood clot inside a blood vessel that subsequently travels through the blood stream from the site where it formed to another location in the body, generally leading to vascular occlusion at the distant site. "While there was no relation to biomarkers of endothelial function, a weak inverse association with D-dimer was in accord with previous reports on a tendency of thromboembolism in GPx3 deficiency." (PMID 39765894, 2024). "Studies in the literature have reported that selenium and/or GPx3 is inversely associated with oxidative stress, inflammation, endothelial function, and thromboembolism." (PMID 39765894, 2024). "In addition, we intended to explore possible associations between GPx3 status and biomarkers of inflammation, oxidative stress, cardiac function, and thromboembolism." (PMID 39765894, 2024).
trichinellosis (1 paper, 2022). "A high upregulation of antioxidant defence enzymes in the NC, out of which GPX3 and SOD3 show extracellular location, well explains another long-known phenomenon of trichinellosis being accompanied by an increase in the antioxidant activities in the muscles and blood of infected animals." (PMID 36478989, 2022).
tuberculosis (1 paper, 2025). A chronic, recurrent infection caused by the bacterium Mycobacterium tuberculosis. "Consistently, our ELISA validation results confirmed that the plasma GPX3 level specifically increased during active tuberculosis and gradually returned to the baseline level after cure." (PMID 41428679, 2025).
upper tract urothelial carcinoma (1 paper, 2023). "Therefore, BEN patients carrying variant GPX3 genotype should be more frequently monitored for possible upper tract urothelial carcinoma development." (PMID 37629712, 2023).
urothelial bladder carcinoma (1 paper, 2023). "Integrated pan-cancer analysis discussed that GPX3 was under expressed in 22 of 34 examined tumor tissue samples, including urothelial bladder carcinoma." (PMID 37629712, 2023).
urothelial carcinoma (1 paper, 2023). A malignant neoplasm derived from the transitional epithelium of the urinary tract (urinary bladder, ureter, urethra, or renal pelvis). "Regarding GPX3 rs8177412 polymorphism, the gene variant that confers lower expression is associated with significant increase in upper urothelial carcinoma risk." (PMID 37629712, 2023). "Due to the fact that GPX3 is primarily expressed in kidney tissue and plays a role in the initiation and progression phase of renal carcinogenesis, we also analyzed the polymorphism of this important antioxidant enzyme in terms of BEN and BEN-associated urothelial carcinoma risk." (PMID 37629712, 2023).
urothelial cell carcinoma (1 paper, 2023). "This study presents comprehensive analysis of the significance of antioxidant gene polymorphisms (Nrf2 rs6721961, KEAP1 rs1048290, GSTP1AB rs1695, GSTP1CD rs1138272, GPX3 rs8177412 and MDR1 rs1045642) in BEN development and associated urothelial cell carcinoma." (PMID 37629712, 2023).
venous thromboembolism (1 paper, 2025). Occlusion of the lumen of a vein by a thrombus that has migrated from a distal site via the blood stream. "Von Willebrand factor (vWF), PDGFB, HIVEP1, and GPX3 have been identified as biomarkers associated with venous thromboembolism in the VEBIOS cohort, with the associations of vWF and PDGFB replicated in FARIVE." (PMID 39940903, 2025).
viral pneumonia (1 paper, 2021). Inflammation of the lung parenchyma that is caused by a viral infection. "With the aid of the discovered biomarkers, we concluded that HYQ has a specific effect on viral pneumonia such as elevated galectin-3-binding protein (Lgals3bp) and glutathione peroxidase 3 (Gpx3) levels in blood." (PMID 34867309, 2021). "Our present study indicates that HYQ can specifically regulate Lgals3bp and Gpx3, thus exerting a good protective effect against viral pneumonia." (PMID 34867309, 2021). "Overall, HYQ may have a specific effect on viral pneumonia such as elevated Lgals3bp and Gpx3 levels in the blood." (PMID 34867309, 2021). "Thus, in some cases, HYQ may be a promising alternative treatment for viral pneumonia, and Gpx3 may be another specific signature regulated by HYQ against viral pneumonia." (PMID 34867309, 2021).
tumor (135 papers, 2009 to 2026). "Enrichment analysis revealed that GPX3 is significantly associated with antioxidant and peroxidase activities, suggesting that dysregulated oxidative stress contributes to tumor progression." (PMID 41170198, 2025). "In contrast, low GPX3 expression is associated with immune response pathways, highlighting its potential involvement in immune evasion or modulation within the tumor microenvironment." (PMID 40092686, 2025). "This review focuses on the expression, regulation and evolution of GPX3 in non-neoplastic diseases, assesses its potential as a prognostic and diagnostic biomarker and explores new therapeutic avenues targeting GPX3." (PMID 38927092, 2024). "Our findings suggested that high GPX3 expression was associated with advanced clinical stage, suggesting that it is a tumor promotor in GC." (PMID 38042786, 2023). "In vitro experiments, GPX3 expression is associated with cancer cell sensitivity to oxidant and platinum-based chemotherapy and is involved in tumor metastasis in oxidative environments." (PMID 36845676, 2023). "These subsets generally do not show obvious differences in ROS or transporter gene expression associated with tumor pathology (except, perhaps, for GPX3)." (PMID 35906899, 2023). "Studies had reported that low expression of GPX3 was associated with poor prognosis and chemoresistance in several tumor types." (PMID 34660806, 2021). "Several studies have demonstrated that loss of GPx3 expression within tumor tissues is associated with poor patient prognosis and chemotherapeutic resistance." (PMID 32781581, 2020). "Ultimately, we performed gene set enrichment analysis (GSEA), protein-protein interaction (PPI) networks, and Bayesian networks (BNs) to explore the underlying mechanisms by which ECM1, CRYAB, CGNL1, and GPX3 are involved in tumor progression." (PMID 32292720, 2020). "The anti-tumor properties of GPx3 have been largely associated with a loss of oxidant scavenging, concomitant increases in oxidative stress and pro-tumorigenic changes including genomic instability, as well as redox dependent signaling." (PMID 32781581, 2020). "Gpx3-deficient mouse models exhibit increased tumor incidence, as well as altered immune modulation of the tumor microenvironment." (PMID 32414091, 2020). "Further, it is presently unclear if a loss of GPx3 drives compensatory increases in other antioxidant enzymes in tumor cells." (PMID 32781581, 2020). "It has not been investigated if these have functional consequences, but due to their low frequency it is unlikely that somatic GPX3 mutations contribute significantly to observed decreases in GPx3 expression and activity in tumor cells." (PMID 32781581, 2020). "Loss of GPx3 increases proliferation, decreases apoptosis and enhances Wnt/β-catenin signaling in tumor tissues." (PMID 32781581, 2020). "Studies using global GPX3 knock-out mice have demonstrated that systemic loss of plasma GPx3 expression aids in tumor initiation." (PMID 32781581, 2020). "Downregulation of GPx3 affects tumor progression and metastasis and is associated with liver and heart disease." (PMID 33322741, 2020). "In HCC, low plasma GPx3 levels are associated with increased tumor recurrence and shorter disease-free survival periods after liver resection." (PMID 32781581, 2020). "Systemic GPX3 loss in mice was shown to promote tumor initiation and accelerate inflammatory colonic tumorigenesis." (PMID 33050144, 2020). "Screening TCGA data sets for somatic mutational signatures suggests that only a very low number of tumor specimens have missense mutations in the GPX3 coding region (somatic mutation rate of TCGA tumors: 0.3%; cBioPortal.org)." (PMID 32781581, 2020). "Previous studies suggest that the tumor suppressor activity of GPx3 is associated with ROS inactivation, which protects cells from genetic mutation and oxidation of proteins involved in carcinogenesis." (PMID 30260967, 2018).
tumor (continued). "Among those genes, GPX3, which encodes a glutathione peroxidase, an antioxidant enzyme and putative tumor suppressor that defends cells against ROS, was the most significantly upregulated." (PMID 28928421, 2017). "Of note, we observed mRNA downregulation, promoter hypermethylation and DNA copy number loss of GPX3 in a number of tumor-adjacent “normal" gastric mucosae samples." (PMID 23071548, 2012). "We found that downregulated GPX3 caused tumor cells to be more sensitive to oxidants." (PMID 36845676, 2023). "To date, studies on the GPX3 gene, which is a target gene of NRF2, have mainly focused on cancers, including colitis-associated carcinoma; for example, Gpx3-deficient mice exhibited increased tumor number and inflammation, suggesting a protective role of GPX3 in colitis-associated carcinoma." (PMID 37170220, 2023). "This study suggested that a decrease in GPX3 expression was associated with a more favorable prognosis, while an increase in GPX3 expression was significantly linked to tumor progression, deviating slightly from the prognostic patterns observed in tumor suppressor genes." (PMID 37790850, 2023). "By the same token, the question arises in terms of whether the polymorphism of the NRF2, GSTM3, SOD2 and GPX3 genes can affect the tumor progression, the prognosis of patients with testicular GCT and eventually the response to systemic chemotherapy." (PMID 35205816, 2022). "High GPX3 expression was associated with poorer overall patient survival and increased tumor stage." (PMID 33987033, 2021). "However, as discussed in Section 3.2, high GPx3 expression within serous ovarian adenocarcinoma tumor tissues is conversely associated with poor prognosis and increased tumor stage." (PMID 32781581, 2020). "Instead, as illustrated in Section 3.2, changes in GPx3 expression may be associated with the tumor cells themselves." (PMID 32781581, 2020). "Further studies are needed to examine how loss or gain of GPx3 specifically affects oxidant scavenging and redox signaling in the extracellular tumor microenvironment, and how GPx3 might be targeted for therapeutic intervention." (PMID 32781581, 2020). "Loss of GPx3 expression has been linked to promoter hypermethylation in several tumor tissues." (PMID 32781581, 2020). "Different studies suggested that GPX3 expression may have an impact on the pathogenesis of various tumors and that it serves as a tumor suppressor gene and its deficiency interferes with tumorogenesis." (PMID 33369453, 2020). "Several studies have reported a decrease or loss of GPx3 expression in tumor tissues." (PMID 32781581, 2020). "To examine whether the tumor suppressive function of GPx3 is associated with its antioxidant activity, we subjected cells to serum starvation to induce oxidative stress." (PMID 30260967, 2018). "GPX3 methylation status was significantly associated with higher tumor nuclear grade (p = 0.014)." (PMID 25970749, 2015). "Interestingly, loss of GPX3 contributes to high infiltration of tumor associated macrophages that support tumor survival in GPX3 knockout mice model." (PMID 24790704, 2014). "In vivo xenograft and metastatic models showed that GPx3 suppressed tumor growth and metastasis, and these effects were partially reversed by DKK1." (PMID 42125307, 2026). "Prior studies have linked several genes (LGALS8, PTPN12, YTHDC2, APOBEC3G, GPX3, RASA3, and TSPAN4) to immune responses, highlighting the impact of the tumor microenvironment (TME) on DCIS." (PMID 41020869, 2025). "The single-cell dataset showed significant under-expression of ADH1B, ADH4, CYP19A1, and GPX3 in tumor samples." (PMID 41031088, 2025). "GPX3, in prostate cancer, this gene is either deleted or methylated, leading to the suppression of tumor growth and metastasis." (PMID 40092686, 2025). "For instance, SELENOI was mostly upregulated in tumor tissues, whereas GPX3 downregulated; the selenoprotein family tended to be downregulated in CHOL but upregulated in UCEC." (PMID 39919065, 2025).